SFRP4 (secreted frizzled related protein 4)
Diseases named in the same sentence as SFRP4 in open-access papers (continued):
Sharing a sentence is not in itself a finding about the gene and the disease.
type 2 diabetes (17 papers, 2013 to 2025). "SFRP4, an inhibitor of the Wnt/β-catenin signaling pathway, has been associated with reduced diabetic nephropathy in type 2 diabetes." (PMID 40193283, 2025). "Among these candidates, secreted frizzled-related protein 4 (SFRP4) stands out as the largest member of the SFRP family and has been strongly associated with various diseases, including obesity, type 2 diabetes, and malignancy." (PMID 38808330, 2024). "Meanwhile, SFRP4 expression levels were significantly elevated in obese and type 2 diabetic patients, and increased β-cell dysfunction and suppressed insulin secretion." (PMID 36036283, 2022). "Third, SFRP4 is overexpressed in the islets of patients with type 2 diabetes and is considered a marker of early beta cell dysfunction." (PMID 32657640, 2020). "Sfrp4 is a Wnt pathway inhibitor that is involved in many diseases including obesity, type 2 diabetes, cancer, and psoriasis." (PMID 31791390, 2019). "First, SFRP4 is overexpressed in obese individuals and patients with type 2 diabetes." (PMID 32657640, 2020). "Furthermore, they found that not only type 2 diabetes patients but also patients who later developed type 2 diabetes had higher serum SFRP4 levels than the controls, although the sample size was small." (PMID 29037197, 2017). "Elevated circulating levels of sFRP4 have also been observed several years before a diagnosis of type 2 diabetes, where it may play a critical role in linking islet inflammation with impaired insulin secretion." (PMID 28637297, 2017). "We also measured the novel hormones SFRP-4, a biochemical harbinger of type 2 diabetes, and irisin, the myokine that may mediate beneficial effects of exercise, and bile acids, implicated in regulation of energy expenditure." (PMID 28694840, 2017). "Thus, SFRP4 may be an attractive target for alleviating the pathological development of type 2 diabetes and fatty liver." (PMID 34489867, 2021). "Abdominal adipose tissue (AbdAT) levels of thirteen microRNAs (miRNAs), SFRP4, and VEGF in lean nondiabetic subjects (n = 7), subjects with obesity (n = 5), and subjects with obesity and type 2 diabetes (T2DM) (n = 5) were measured by qPCR." (PMID 29721017, 2018).
Obesity (15 papers, 2015 to 2025). Accumulation of substantial excess body fat. "Sex-dependent obesity-associated metabolic complications has been correlated to sex-dependent modulation of two major genes involved in adipogenesis (Sfrp4) and in TG synthesis (Dgat2)." (PMID 34997206, 2022). "We hypothesize that miRNAs might be involved in the regulation of SFRP4 causing adipose tissue rarefaction and inflammation and ultimately leading to insulin resistance in patients with obesity." (PMID 29721017, 2018). "We have also demonstrated that the antiangiogenic factor secreted frizzled-related protein 4 (SFRP4) is associated with adipose tissue rarefaction (capillary drop out) and may lead to inflammation and ultimately insulin resistance in people with obesity." (PMID 29721017, 2018). "Secreted frizzled-related protein 4 (SFRP4), has been recently identified as a potential early biomarker of T2D related to obesity, due to its association with low grade inflammation in adipose tissue and impaired glucose metabolism." (PMID 38834984, 2024). "Although in the present work the association of SFRP4 levels with WC or WHR was lost, it is important to mention that we did not measure visceral fat, which is a more accurate indicator of obesity than WC or WHR." (PMID 38834984, 2024). "The molecular docking and MD simulation investigations were carried out against phytochemicals with anti-diabetic and anti-obesity properties to shortlist the best SFRP4 inhibitor." (PMID 37943820, 2023). "SFRP4 is released from WATs in the period of obesity, leading to elevated production of adiponectin." (PMID 35290144, 2022). "SFRP4 is the largest member of the SFRP family and is associated with many diseases, including obesity, cancer and type 2 diabetes (T2D)." (PMID 35290144, 2022). "In summary, our data showed that SFRP4 overexpression altered adipocyte size and adipokine secretion, possibly affecting adipocyte differentiation, obesity, and glucose metabolism." (PMID 32657640, 2020). "(b) These results emphasize the roles of AbdAT miRNAs (i.e., miR-24, miR-30d, and miR-146a) and SFRP4 in regulating mechanisms that govern AbdAT remodeling and systemic insulin sensitivity in obesity and T2DM." (PMID 29721017, 2018). "We have also shown the potential biomarker utility of the circulating SFRP4 protein in an independent cohort by demonstrating its differential abundance in plasma from subjects with obesity, prediabetes, and T2DM." (PMID 29721017, 2018). "This study suggests a novel association between the elevated levels of miRNAs miR-24, miR-30d, and miR-146a (apparently coregulated) and the level of SFRP4 transcript in AbdAT of subjects with obesity and T2DM." (PMID 29721017, 2018). "High serum levels of sFRP4 have also been previously reported in multiple pathologic conditions, including obesity and osteoporosis." (PMID 28637297, 2017). "SFRP4 is secreted by multiple tissues including adipose tissue, which contributes the elevated circulating SFRP4 level in obesity." (PMID 29069795, 2017). "Recent research indicates RV and quercetin, at varying doses, decrease inflammation by impacting SFRP4, a protein involved in obesity, diabetes, and pancreatic inflammation, thus highlighting a connection between obesity-driven inflammation and dysfunctional insulin response." (PMID 40732979, 2025). "We therefore hypothesize that genetic variation in SFRP4 could be related to metabolic disorders, specifically obesity." (PMID 38834984, 2024). "However, it is still unclear how exactly SFRP4 regulates the secretion of adipokines in the adipose tissue in vivo, an event that is closely related to the pathogenesis of obesity and insulin resistance." (PMID 32657640, 2020). "The mechanism through which these molecules exert their effects on obesity is still unclear, but these studies suggest that miRNA-regulated adipose tissue-secreted SFRP4 is related to adiposity and contributes to global insulin resistance in a paracrine and endocrine manner." (PMID 29721017, 2018).
Obesity (continued). "Taken together, our current and previously published work discussed in this manuscript suggests an important role for the apparently coregulated (in AbdAT) miRNA trio miR-24/miR-30d/miR-146a and SFRP4 in obesity-related pathological events leading to insulin resistance and T2DM." (PMID 29721017, 2018). "SFRP4 plays important roles (e.g., may inhibit vascularization and promote tissue inflammation) in obesity and T2DM pathophysiology." (PMID 29721017, 2018). "This could develop better control over the obesity and related metabolic diseases such as T2 diabetes, wherein sFRP4 levels are shown to be elevated." (PMID 25714610, 2015). "(a) AbdAT levels of miR-24, miR-30d, and miR-146a are elevated in subjects with obesity and T2DM and positively correlate with the level of SFRP4 transcripts in the same tissue." (PMID 29721017, 2018). "This implies that in AbdAT of subjects with obesity and T2DM, the elevation of SFRP4 levels may induce the expression of miR-146a as a feedback regulatory loop to self-limit the potentially detrimental overexpression of SFRP4." (PMID 29721017, 2018).
gastric cancer (14 papers, 2011 to 2025). A primary or metastatic malignant neoplasm involving the stomach. "Secreted Frizzled-related protein 4 (SFRP4) has been identified as a patient-level biomarker of the stem-like subtype of gastric cancer (GC), which is associated with poor prognosis and resistance to chemotherapy." (PMID 40565036, 2025). "SFRP4 is an independent prognostic factor and is significantly associated with poor prognosis in gastric cancer patients." (PMID 35847366, 2022). "Using the TISIDB database to evaluate the link between SFRP4 expression and the immune milieu, we found a clear association between SFRP4 expression levels and lymphocytes, immunomodulators, and chemokines in gastric cancer patients." (PMID 35847366, 2022). "Our further survival study revealed that elevated SFRP4 expression in gastric cancer is associated with a worse prognosis, with a 5-year OS rate of 39.81%." (PMID 35847366, 2022). "The chi-square test was used to examine the relationship between SFRP4 expression and PD-L1 expression in gastric cancer tissues, and high SFRP4 expression was determined to be positively linked with the degree of PD-L1 expression." (PMID 35847366, 2022). "Using online databases, we found that SFRP4 expression was higher in gastric cancer tissues and substantially was associated with the immune microenvironment." (PMID 35847366, 2022). "Despite this, we observed select consistent cancer-specific or gene-specific effects: For example, high expression of any SFRP was associated with poor prognosis in stomach cancer; and high expression of SFRP4 only associated with poor outcomes (p < 0.05)." (PMID 28218291, 2017). "Importantly, pharmacological inhibition of PKA significantly reduced SFRP4 phosphorylation and suppressed stemness-associated phenotypes, such as sphere formation, migratory capacity, and chemoresistance, in gastric cancer cells." (PMID 40565036, 2025). "Furthermore, online database mining revealed that several different lymphocytes, immunomodulators, and chemokines in gastric cancer tissues were substantially linked with high SFRP4 expression." (PMID 35847366, 2022). "SFRP4 expression was elevated in gastric cancer tissues and linked to a poor prognosis (P=0.021)." (PMID 35847366, 2022). "We investigated SFRP4 expression and its effect on overall survival (OS) in 137 patients with gastric cancer." (PMID 35847366, 2022). "The TIMER database was used to investigate the relationship between SFRP4 expression and immune cell infiltration in gastric cancer." (PMID 35847366, 2022). "In both univariate and multivariate analyses, SFRP4 was found to be an independent prognostic factor for gastric cancer." (PMID 35847366, 2022). "SFRP4 was found to be expressed in the cell membrane and cytoplasm in both gastric cancer and paraneoplastic tissues but was minimally expressed in the nucleus." (PMID 35847366, 2022). "We found that high tumor SFRP4 expression (P=0.024), family history of gastric cancer (P=0.005), high CD4 expression (P=0.009), and high CD8+T expression (P=0.048) were risk or protective factors for OS in patients in univariate analysis." (PMID 35847366, 2022). "Based on our findings and database analysis, these results indicate that SFRP4 can regulate the immune microenvironment of gastric cancer." (PMID 35847366, 2022). "This study finds that SFRP4 is an oncogenic driver that can predict patient survival time in gastric cancer, as well as an important immune-related factor." (PMID 35847366, 2022). "Recently, single patient classifier (SPC) genes, such as secreted frizzled-related protein 4 (SFRP4) and caudal-type homeobox 1 (CDX1), were associated with prognosis and chemotherapy response in stage II–III gastric cancer." (PMID 35683460, 2022). "High SFRP4 expression (P=0.011) and having a family history of gastric cancer (P=0.011) were found to be independent predictors of OS in patients with gastric cancer in multivariate analysis." (PMID 35847366, 2022).
gastric cancer (continued). "Based on these findings, we believe that SFRP4 interacts with immune cell infiltration throughout the progression of gastric cancer, influencing the immune microenvironment." (PMID 35847366, 2022). "SFRP4 is an oncogenic driver that can predict patient survival time in gastric cancer, as well as an important immune-related factor." (PMID 35847366, 2022). "The group with high SFRP4 expression in gastric cancer tissues had a poorer 5-year OS rate (P=0.021), where the 5-year OS rates in the low and high SFRP4 expression groups were 60.02% and 39.81%, respectively." (PMID 35847366, 2022). "We also found that SFRP4 expression status was an independent predictive factor for gastric cancer patients in univariate and multifactorial models." (PMID 35847366, 2022). "The goal of this research was to explore the expression of SFRP4 in gastric cancer, its clinical significance, and its relationship with the tumor immune microenvironment." (PMID 35847366, 2022). "Using tissue microarray technology, we discovered that SFRP4 expression was significantly elevated in gastric cancer tissues compared to paracancerous tissues and tumor infiltration was deeper in patients with high SFRP4 expression." (PMID 35847366, 2022). "The goal of this research was to determine the significance of SFRP4 and the immune microenvironment in the treatment and prognosis of gastric cancer." (PMID 35847366, 2022). "High SFRP4 expression in gastric cancer patients likely corresponds with positive PD-L1 expression, resulting in a poor prognosis." (PMID 35847366, 2022). "Regarding the association between SFRP4 and gastric cancer, the elevated expression of SFRP4 was significantly related to poor prognosis in stage II–III gastric cancer." (PMID 35683460, 2022). "Our research aimed to explore the expression of SFRP4 in gastric cancer, its prognostic significance, and its relationship with immune cell infiltration." (PMID 35847366, 2022). "CD8+T-cell infiltration was shown to be greater in gastric cancer tissues with elevated SFRP4 expression (P=0.015)." (PMID 35847366, 2022). "Expression of secreted frizzled-related protein 4 (SFRP4) was identified as directly proportional to gastric cancer invasion." (PMID 33277667, 2021). "Consistent with current literature, we found that the expression of SFRP4 and gastric cancer stages were positively correlated." (PMID 34205081, 2021). "We find that reducing SFRP4 levels using shRNA resulted in the reduced invasion of different subtypes of gastric cancers in vitro." (PMID 33277667, 2021). "In conclusion, we have shown that SFRP4 is over-expressed in the majority of gastric cancers and its high expression leads to a poor outcome." (PMID 33277667, 2021). "Recent studies comparing gastric cancer and normal tissue have identified a number of genetic markers, including diagnostic markers [NF2, INHBA, SFRP4], prognostic markers [CD9, CDH17, PDCD6], and gastric cancer-associated genes [MUC13, CLDN1, Ki67 and CD34]." (PMID 22133303, 2011). "Moreover, H-89 treatment significantly reduced sphere-forming efficiency, confirming that PKA-dependent phosphorylation of SFRP4 is essential for its nuclear localization, β-catenin binding, and the acquisition of stemness traits in gastric cancer." (PMID 40565036, 2025). "High-expressed SFRP4, which correlates with a poor prognosis of gastric cancer, can activate the Wnt pathway to promote tumor progression and predict a poor survival of patients suffering from gastric cancer." (PMID 37007021, 2023). "Our results indicate that SFRP4 expression is upregulated in gastric cancer tissues." (PMID 35847366, 2022). "However, in gastric cancer, SFRP4 expression is upregulated by the reduced methylation, and high expression of SFRP4 could promote cell viability and proliferation and inhibit apoptosis, as well as activate the Wnt pathway and promote tumor progression." (PMID 38239300, 2024).
gastric cancer (continued). "Aberrant activation of the Wnt/β-catenin signaling pathway is closely associated with the development of adenomyosis, so the role of SFRP4 in adenomyosis may be similar to that in gastric cancer, activating the Wnt signaling pathway and promoting cell proliferation, invasion, and metastasis." (PMID 38239300, 2024). "Gastric cancer and paracancerous tissue specimens from surgically resected gastric cancer patients were collected to construct tissue microarrays, and immunohistochemistry was used to detect the expression of SFRP4, PD-L1, CD3+T, CD4+T, and CD8+T in these microarrays." (PMID 35847366, 2022). "The expression of SFRP4 and its role in gastric cancer development remains unknown." (PMID 35847366, 2022). "SFRP4 may be important for guiding immunotherapy in gastric cancer patients." (PMID 35847366, 2022). "This study also found that SFRP4 levels in patients after curative resection of gastric cancer predicts GC recurrence at an early stage." (PMID 33277667, 2021). "SFRP4 was overexpressed in the majority of gastric cancers and absent in normal gastric tissue." (PMID 33277667, 2021). "Intersection genes TREM2, CTHRC1, BGN, NOX4, GPX3, HEYL, and SFRP4 from the GSE72305 and GSE103236 datasets, which were differentially expressed in the normal gastric mucosa than in gastric cancer cells and in lymph node free to lymph node metastatic GC." (PMID 33976737, 2021).